VWF (von Willebrand factor)
Diseases named in the same sentence as VWF in open-access papers (continued):
Sharing a sentence is not in itself a finding about the gene and the disease.
Stroke (179 papers, 2003 to 2026). Sudden impairment of blood flow to a part of the brain due to occlusion or rupture of an artery to the brain. "Higher vWF levels are linked to poorer outcomes and can assist in predicting stroke severity and recovery." (PMID 40142325, 2025). "Traditional energy sources such as radiofrequency (RF) and cryoballoon (CB) ablation can induce a procoagulant response, with elevated tissue plasminogen activator and von Willebrand factor (vWF) levels, predisposing patients to thrombosis and stroke." (PMID 41283474, 2025). "Increased platelet activation and inflammatory markers such as C-Reactive Protein (CRP), interleukins, and Von Willebrand Factor (VWF) in AF patients have been shown to be associated with stroke." (PMID 39572434, 2024). "Epidemiological and in-vitro data obtained point toward a possible albeit weak association of elevated VWF levels and increased adverse outcomes like stroke and myocardial infarction especially in high-risk individuals." (PMID 39697971, 2024). "A case-control study revealed that VWF levels were high in patients at 3 days after IS and documented the association between stroke severity, age, and sex and VWF levels." (PMID 37274178, 2023). "Plasma lipid peroxides concentration was positively related to ICAM-1 and presence of stroke, whereas platelet lipid peroxides were positively associated with vWF." (PMID 35739962, 2022). "Our findings on the formation of von Willebrand factor (VWF-N) are in line with the previous findings of von Willebrand factor levels, where increased levels have been associated with all-cause mortality, stroke, and first-time coronary heart disease." (PMID 36009558, 2022). "vWF-antigen levels have been associated with first-time coronary heart disease, all-cause mortality, and stroke." (PMID 36009558, 2022). "Another procoagulative agent implicated in migraines related to stroke is the von Willebrand factor (vWF)." (PMID 34900505, 2021). "Increased levels of plasma Von-Willebrand factor (vWF) have been associated with an increased risk of stroke." (PMID 34957252, 2021). "Risk estimates for increased VWF levels ranged from a 0.9-fold to a 4.7-fold increased risk of myocardial infarction and ranged from a 1.0-fold to a 6.7-fold increased risk of stroke." (PMID 34134634, 2021). "The VWF Ag:ADAMTS13 ratio has been highlighted in other thrombotic conditions with higher ratios being associated with inferior outcomes in stroke and cardiac disease." (PMID 33363289, 2021). "Among those that evaluated stroke only outcomes, two studies found that high levels of vWF was linked to a greater risk of stroke." (PMID 32154260, 2020). "Plasma VWF levels > 200% are typically found in patients with myocardial infarction or stroke at high risk of recurrent events and death." (PMID 32636459, 2020). "Dengue virus, an RNA virus similar to coronavirus, is known to stimulate endothelial cells to release VWF, and an association between elevated circulating levels of VWF and stroke has been reported in dengue." (PMID 32552865, 2020). "In accordance with experimental findings, high serum levels of vWF in patients as well as autoantibodies against ADAMTS13 have been identified as risk factors for stroke." (PMID 33123127, 2020). "Of note, despite only constituting 20% of the total vWF protein, platelet vWF alone was sufficient to render mice susceptible to experimental stroke." (PMID 31736950, 2019). "Studies performed in stroke patients revealed that genetic alterations in the GP1bA gene and increased serum levels of vWF are risk factors for stroke, and a predictive factor for long term mortality after acute stroke." (PMID 31736950, 2019). "Taken together, it is clear that levels of ADAMTS13, as well as levels of VWF, are associated with the risk of stroke in the general population." (PMID 31379722, 2019). "Genetic determinants and vWF levels were investigated with respect to overall stroke risk in the large prospective Rotterdam study." (PMID 29847840, 2018).
Stroke (continued). "Data for the impact of vWF levels on stroke outcome and the risk for stroke recurrence came from observational and case–control studies." (PMID 29847840, 2018). "In a much larger sample size, the ‘Atherosclerosis Risk in Communities study’ showed a positive association between baseline vWF levels and the risk of stroke occurrence." (PMID 29847840, 2018). "In this prospective study that followed more than 14,000 patients free of cardiovascular disease for up to 9 years, the risk of stroke in patients in the highest vWF quartile was 1.7 (CI, 1.1–2.7) times higher than in those in the lowest vWF quartile." (PMID 29847840, 2018). "Despite 25% lower vWF levels in type 0 individuals, the stroke risk was higher in patients in the highest vWF quartile with blood group 0 as compared with non-0." (PMID 29847840, 2018). "Increasing vWF levels were associated with a significant increase in the risk of stroke (HR per standard deviation increase: 1.12 [CI, 1.01–1.25])." (PMID 29847840, 2018). "Conversely, people with high VWF levels are at higher risk for venous thromboembolic disease, stroke, and coronary artery disease." (PMID 29416854, 2018). "The association between VWF antigen levels and stroke severity remained significant after adjustments for confounders (current smoking, hsCRP, age) in the statistical model." (PMID 29410644, 2017). "In contrast, NT-proBNP (which is raised in heart failure) was significantly associated with vWF and D-dimer, factors shown to be associated with increased risk of stroke and overall mortality." (PMID 28043678, 2017). "In the present study, we demonstrate that raised vWF levels doubled the risk of stroke, cardiovascular death and major bleeding, and increased (by more than 50%) cardiovascular events and all-cause mortality." (PMID 28134282, 2017). "Elevated levels of FVIII/VWF have been associated with the risk of stroke; however, less evidence is available on the prognostic value of both markers in stroke outcomes." (PMID 29410644, 2017). "In line with our findings, most studies revealed that in the majority of tested patients with AIS, high FVIII and VWF levels were found; moreover, baseline stroke severity, as measured by the NIHSS score was associated with elevated FVIII and/or VWF levels." (PMID 29410644, 2017). "Significant associations were found between vWF and cardiovascular events, stroke, mortality and bleeding." (PMID 28134282, 2017). "On univariate analyses, plasma vWF levels were significantly predictive of cardiovascular events, stroke, all cause-mortality, cardiovascular death and major haemorrhage." (PMID 28134282, 2017). "Limited evidence is available on the possible association of FVIII/VWF levels with the etiology of stroke; moreover, reports are often discordant in this respect." (PMID 29410644, 2017). "A high level of vWF predicts recurrent cardiovascular events, and is also associated with an increased risk of first-ever stroke." (PMID 28570705, 2017). "In one case-control study of 600 stroke patients, chronically increased levels of vWF measured three months after ischemic stroke were associated with cardioembolic or cryptogenic etiology of stroke." (PMID 28570705, 2017). "After adjustment for the CHA2DS2-VAScscore, vWF levels were significantly associated with the incidence of the composite cardiovascular end-point, stroke, all-cause mortality and cardiovascular mortality." (PMID 28134282, 2017). "Gain-of-function mutations in GPIbα contribute to an abnormally high-affinity binding of platelets to vWF and can lead to thrombosis, an accurate complication causing heart attack and stroke." (PMID 22860101, 2012). "In full support of this, we showed that VWF-deficient mice that were reconstituted with a VWF mutant defective in binding to GPIbα retained their protection against stroke." (PMID 21914206, 2011).
Stroke (continued). "Notably, VWF's role in stroke is evidenced by studies showing that VWF deficiency leads to reduced ischemic damage and improved outcomes." (PMID 40356948, 2025). "However, other studies have reported elevated vWF levels in ischemic stroke patients, which are associated with more severe strokes and poorer outcomes at 90 days." (PMID 40135640, 2025). "The current study sought to describe and analyze whether early (<60 days) postoperative von Willebrand factor (VWF) activity assays predict the risk of gastrointestinal bleeding and stroke." (PMID 38896804, 2025). "Therefore, we conclude that these factors collectively represent a positive association between VWF and both stroke severity and poor prognosis in patients with AIS." (PMID 41036279, 2025). "Research indicates that individuals under psychological stress exhibit elevated levels of coagulation factors like fibrinogen and von Willebrand factor (vWF), which are associated with an increased risk of thrombotic events such as myocardial infarction and stroke." (PMID 40486646, 2025). "Additionally, in this study, the VWF: ADAMTS13 ratio was associated with stroke severity and mortality." (PMID 40217918, 2025). "The increase in plasma VWF is predictive of prothrombotic complications and multi-organ system failure associated with reduced survival in the context of severe inflammatory response syndrome, type II diabetes mellitus, stroke and in diverse cardiac diseases." (PMID 38381272, 2024). "Although there may be a temptation to establish a cut-off value for vWF levels that distinguishes stroke risk, this is an oversimplification of the complex process of stroke in AF." (PMID 38397876, 2024). "Furthermore, high levels of circulating vWF are associated with prothrombotic complications, diabetes, stroke, and inflammatory cardiovascular disease." (PMID 37685924, 2023). "The risk of stroke increased with increasing VWF levels, after adjustment for age and sex." (PMID 37274178, 2023). "The von Willebrand factor is another procoagulant implicated in migraines linked to stroke (vWF)." (PMID 36000125, 2022). "Elevated serum sodium levels in a mouse model also increased secretion of von Willebrand factor (vWF) which initiates blood clots, and plasma vWF and stroke risk are positively associated with elevated serum sodium in the Atherosclerosis Risk in Communities Study." (PMID 35954516, 2022). "While individuals with low VWF levels are more prone to mucocutaneous bleeding, individuals with high VWF levels are at higher risk for venous thromboembolic disease, coronary artery disease, and stroke." (PMID 33804754, 2021). "Targeting VWF, on the other hand, may be a more promising approach via reducing stroke recurrence, thrombotic risk, platelet aggregation and VWF-associated inflammation." (PMID 34829993, 2021). "In addition, higher circulating VWFAc were found in patients treated with tPA and in those with greater stroke severity, supporting previous studies showing that increased VWF levels were associated with elevated baseline stroke severity (by the NIHSS score)." (PMID 33692737, 2021). "High levels of vWF are associated with severity of stroke, as well as with poor clinical outcome." (PMID 31701356, 2020). "Some of these are linked to stroke risk and have already been (e.g., renal failure, IL-6, vWF)." (PMID 32154260, 2020). "This also suggests that the differential expression of CD31 and vWF could be responsible for making certain brain regions more susceptible to tissue damage in certain conditions, e.g. stroke or cerebral malaria." (PMID 31935960, 2020). "Consequently, the role of vWF for stroke risk stratification in AF requires additional investigation." (PMID 32154260, 2020). "However, they found that the VWF:ADAMTS13 ratio was significantly associated with stroke severity and modality." (PMID 31379722, 2019). "The VWF:ADAMTS13 ratio has a strong correlation with the risk of stroke." (PMID 31379722, 2019).
Stroke (continued). "The VWF: ADAMTS13 ratio has a stronger correlation with the risk of stroke than either of them." (PMID 31379722, 2019). "As vWF is critically involved in platelet aggregation and thrombus formation upon endothelial activation, it has been studied intensively as a potential risk factor for stroke and stroke-related outcome." (PMID 29847840, 2018). "Moreover, the univariate analysis revealed that VWF:ADAMTS13 ratios were significantly associated with stroke severity (NIHSS: p = 0.048; BI: p = 0.004 and mRS: p = 0.015) and stroke modality (AIS or TIA; p = 0.023)." (PMID 28591212, 2017). "The VWF:ADAMTS13 ratio was significantly associated with stroke severity and modality." (PMID 28591212, 2017). "Moreover, elevated levels of VWF have been associated with increased stroke risk and poor prognosis." (PMID 28713823, 2017). "Indeed, in multivariable regression analysis of clinical data from the Atherosclerosis Risk in Communities Study, serum sodium significantly contributes to prediction of the blood level of vWF and the 10 years Risk of Stroke." (PMID 26042828, 2015). "Also, multivariable analysis of data from Atherosclerosis Risk in Community study demonstrates that serum sodium is an independent predictor in humans of the plasma level of vWF, of the 10 Years Risk of Stroke and of the10 Years Risk of CHD." (PMID 26042828, 2015). "Our study confirms increased VWF levels as a risk factor for cerebrovascular disease and, moreover, suggests that it may represent a potential biomarker for stroke severity, warranting further investigation." (PMID 24937073, 2014). "A higher level of D-dimer and VWF is associated with an increase in the prevalence of stroke." (PMID 24523776, 2013). "One-year changes from baseline values were associated with stroke risk in multivariate analysis for only one biomarker: von Willebrand factor (lowest quintile of change OR 0.66, 95% CI 0.35–1.23; middle quintile, including no change, referent; highest quintile OR 0.95, 95% CI 0.51–1.74; p = 0.04)." (PMID 17571161, 2007). "High vWF levels may be linked to increased stroke severity and poor clinical outcomes." (PMID 40142325, 2025). "Further research is needed to investigate whether vWF plasma concentrations could be used to identify patients with a low CHA2DS2-VASc score who are at moderate risk of stroke or other cardiovascular events and might benefit from oral anticoagulant (OAC) therapy." (PMID 38397876, 2024). "Researchers have also found that elevated sodium chloride increases vWF secretion in vascular endothelial cell cultures, and analysis of the data from the Atherosclerosis Risk in Communities Study revealed that serum sodium is associated with plasma vWF and stroke risk." (PMID 34440945, 2021). "Therefore, screening patients free of stroke at preventive check-ups could help to identify high-risk patients, stratifying them for risk of future stroke based on their vWF levels and/or ADAMTS13 activity." (PMID 29847840, 2018). "In the context of stroke, several platelet‐related factors—such as von Willebrand factor, CD40 ligand, and monocyte–platelet aggregates—have been implicated in poor functional outcomes based on evidence from both basic animal studies and human serum analyses." (PMID 41550466, 2026). "Although vWF is a valuable biomarker for evaluating endothelial damage and thrombosis in stroke, it lacks specificity because it can also be elevated in other conditions, such as cardiovascular diseases, inflammation, and other thrombotic disorders." (PMID 40142325, 2025). "It has been suggested that in the general population, ADAMTS activity, VWF: Ag, and especially the VWF: Ag/ADAMTS13 Ratio, are associated with stroke risk development independently of other factors." (PMID 40217918, 2025). "In women with both stroke and migraine, VWF:Ag levels were increased, while fibrinogen, FIX, and FXI:C were not." (PMID 40022462, 2025).
Stroke (continued). "Although several studies report higher circulating levels of vWF in recent lacunar stroke patients compared to controls, others suggest these levels normalize past the acute‐stroke stage or are comparable to patients of non‐lacunar ischemic stroke." (PMID 40275856, 2025). "This study revealed a correlation between elevated levels of VWF and both poor prognosis and stroke severity." (PMID 41036279, 2025). "Overall leukocyte levels mediate the influence of blood glucose levels, heart dysfunction, and vitamin B12 on content VWF in thrombi in stroke patients." (PMID 40625905, 2025). "Bongers and colleagues in their case–control study of 124 patients with ischemic stroke and 125 matched controls, found that VWF: Ag levels were significantly higher in stroke patients in comparison to controls (p = 0.002)." (PMID 40217918, 2025). "While HHT is inherently a bleeding disorder, patients are at a higher risk of venous thromboembolism (VTE) and stroke, which is particularly due to high levels of factor VIII and von Willebrand factor (vWF)." (PMID 41523403, 2025). "This assay measured the ratio of collagen‐bound VWF (VWF: CBA) over the total antigen levels of VWF (VWF: Ag) normalized to the non‐stroke controls." (PMID 39972966, 2025). "In this prospective study, the association between ADAMTS13 activity, VWF: Ag, and the VWF: Ag/ADAMTS13 Ratio and stroke outcomes was examined." (PMID 40217918, 2025). "The GPIbα extracellular domain interacts with the von Willebrand factor (VWF), initiating platelet adhesion, hemostasis, and thrombus formation, which can lead to serious conditions, including myocardial infarction and stroke." (PMID 40491968, 2025). "VWF is large multimeric glycoprotein released by activated endothelial cells during stroke, mediating platelet adhesion to injured or activated vascular walls and contributing to thrombosis." (PMID 40625905, 2025). "The results showed that patients who experienced a severe stroke had higher vWF levels (p < 0.05), and a significant positive correlation was observed using multiple linear regression analysis (β = 0.267, 95% CI [0.058–0.476], p = 0.013)." (PMID 40135640, 2025). "The ratio of the area of the von Willebrand factor (vWF)-positive staining to the total lesion area in the Stroke + Kr group was almost twice that in the control group, with 0.11 (0.10; 0.13) versus 0.06 (0.04; 0.07) (p = 0.029)." (PMID 38540249, 2024). "It has been reported that the improvement in stroke severity is associated with neuroplasticity, which, in turn, relates to VCAM-1, MMP-9, S100β, and vWF." (PMID 39599732, 2024). "Another study suggested that patients with AF who received OAC treatment and had a history of stroke exhibited changes in their vWF levels, activity, and molecular structure." (PMID 38397876, 2024). "Animal model studies have shown that vWF has a regulatory action for cerebral vascular permeability closely related to stroke and inflammatory processes in the brain." (PMID 35207321, 2022). "A propensity matched sample from > 3000 Salford Kidney Study (SKS) patients, differentiated by previous stroke at study recruitment, had stored plasma analyzed for interleukin- 6 (IL-6), Von Willebrand Factor (VWF) and C-reactive protein (CRP)." (PMID 35042473, 2022). "VWF was proposed and demonstrated to be a biomarker of vascular injury in cardiovascular diseases, such as diabetes, stroke, and coronary artery disease." (PMID 35966750, 2022). "Our study identified four proteins (ceruloplasmin, SERPINA1, vWF, and F13B) that commonly differentiated total stroke, IS, and ICH from healthy control subjects." (PMID 36237606, 2022). "Patients with high levels of VWF showed more severe stroke, dismal clinical outcomes, and an increased chance of recurrent stroke." (PMID 35207321, 2022). "First, the amounts of extracellular DNA and VWF are exceptionally high compared to what is typically found in stroke thrombi." (PMID 33618719, 2021).